ENSG00000296661 (novel transcript)
Gene: Long non-coding RNA gene on chromosome 9 (38,079,552 to 38,082,668, forward strand). Ensembl gene ENSG00000296661.
Gene Ontology:
Biological process: SRP-dependent cotranslational protein targeting to membrane, signal sequence recognition
Cellular component: signal recognition particle, endoplasmic reticulum targeting